INS (insulin)
Diseases named in the same sentence as INS in open-access papers (continued):
Sharing a sentence is not in itself a finding about the gene and the disease.
Hypoglycemia (continued). "This, in turn, will lead to a change in levels of insulin and other proteins (IGF-1, IGF-binding proteins...) causing hypoglycaemia." (PMID 39931615, 2025). "Experiments in diabetic rats showed that FA-decorated PEGylated liposomes achieved insulin bioavailability of 19.08% and sustained hypoglycemia for over 24 h." (PMID 41471078, 2025). "By autonomously adjusting insulin delivery, it minimises nocturnal hypoglycaemia and stabilises glucose fluctuations, which are often inadequately managed by traditional insulin therapy." (PMID 41157817, 2025). "Persistent hypoglycemia with normal serum insulin levels required glucose infusion of up to 12 mg/kg/minute." (PMID 40137958, 2025). "Nevertheless, hypoglycemia can occur when SGLT2i is prescribed in combination with insulin or any insulin-dependent or sensitizing antidiabetic medication." (PMID 41009577, 2025). "CGM/SIP combined data revealed patterns of nocturnal hypoglycemia due to physician-overestimated basal requirements and hypoglycemia related to administering meal-size insulin doses with snacks." (PMID 40142601, 2025). "A link between insulin therapy-related hypoglycaemia during pregnancy and neurocognitive development of the offspring has also been suspected." (PMID 40613865, 2025). "Standardized preparation of glucose–insulin therapy is essential to prevent errors, such as hypoglycemia from incorrect dosing." (PMID 40705102, 2025). "Insulin therapy carries well-documented risks, including weight gain, hypoglycemia, and local complications such as injection-induced lipohypertrophy, which increase both morbidity and healthcare costs." (PMID 41031090, 2025). "Hypoglycemia is a frequent and clinically significant occurrence among T2DM patients in Rwanda, particularly associated with insulin therapy and CV comorbidities." (PMID 41393767, 2025). "The next pharmacological agent is diazoxide that activates ATP-sensitive potassium channels and is used in the treatment of hyperinsulinemia and hypoglycemia due to its ability to inhibit insulin release." (PMID 41155561, 2025). "In our case, the patient presented with a rapidly growing breast mass and episodes of hunger‐related hypoglycemia characterized by abnormally elevated insulin levels." (PMID 40550558, 2025). "In response to elevated glucose, β-cells release insulin to stimulate glucose disposal in peripheral tissues while glucagon, produced by α-cells, stimulates hepatic glucose output to prevent hypoglycemia between meals." (PMID 41093076, 2025). "In parallel, measuring ketone bodies (especially β‐hydroxybutyrate) is important because low ketone levels during hypoglycemia indicate persistent insulin or insulin‐like hormone activity that suppresses lipolysis and ketogenesis." (PMID 40124204, 2025). "This often presents as symptomatic fasting hypoglycemia, endogenous insulin and ketones suppression, and an elevated IGF-2/IGF-1 ratio." (PMID 40727482, 2025). "The iLet BP system also excels in nighttime glucose control, minimising nocturnal hypoglycaemia and stabilising glucose fluctuations, which are often inadequately managed by traditional insulin therapy." (PMID 41157817, 2025). "Endocrine comorbidities, including hypothyroidism and hypogonadism, further complicate the clinical picture by impairing counter-regulatory responses to hypoglycemia and altering insulin insensitivity." (PMID 41040769, 2025). "In our case, the hypoglycemia was from endogenous hyperinsulinemia, indicating increased secretion of insulin by the β cells." (PMID 40083398, 2025). "Diagnosis of insulin and insulin secretagogue-induced hypoglycemia requires biochemical evidence of insulin-mediated hypoglycemia with a few unique features." (PMID 40648766, 2025). "Considering the increased risk of hypoglycemia in cirrhotic patients, those on insulin therapy require a CGM and appropriate insulin dose reduction with the start of SGLT2i treatment." (PMID 40704640, 2025).
Hypoglycemia (continued). "Our findings highlight the necessity of carefully monitoring blood glucose levels and adjusting insulin doses in active young individuals, particularly to manage nocturnal hypoglycemia due to potential delayed hypoglycemic events from PA." (PMID 38954647, 2025). "Many modern systems combine pumps with CGM to create “sensor-augmented” pumps, which feature automated insulin suspension in response to pre-specified thresholds of hypoglycaemia." (PMID 40718205, 2025). "By February 2024, ketone bodies showed values of 0 mmol/L, suggesting insulin-mediated hypoglycemia." (PMID 40981133, 2025). "Management includes replenishing fluids, correcting electrolyte abnormalities, insulin replacement supplemented by glucose to avoid hypoglycemia." (PMID 40585463, 2025). "In people with T2D, risks of hypoglycemia and weight gain with insulin and sulfonylurea rendered metformin the drug of choice in reducing the macrovascular risk of MI and CV death." (PMID 40861717, 2025). "Hypoglycaemia (low blood glucose) is a common side-effect of insulin treatment, due to excess insulin relative to blood glucose." (PMID 40688059, 2025). "For those with T1D, distress can arise from or be amplified by the constant nature of monitoring blood glucose, administering insulin, making decisions about food, eating, and activity, and fearing the possibility of life-threatening hyper- or hypoglycemia." (PMID 40564574, 2025). "Secondary outcomes included changes in fasting plasma glucose, insulin dose, hypoglycemia incidence, and SMBG adherence." (PMID 39924297, 2025). "The study compared maternal outcomes such as HbA1c > 9%, insulin use and incidences of hypoglycemia, Diabetic Ketoacidosis (DKA), and acute illness between both groups." (PMID 40078500, 2025). "Hormones such as glucagon and adrenaline, realized primarily in response to hypoglycemia, decrease INS secretion and counter the effects of INS by stimulating glucose production and release from the liver." (PMID 40052150, 2025). "Patients with T2D, particularly those on insulin or SU, are more vulnerable to hypoglycemia during this time of the day." (PMID 40963529, 2025). "The family was educated on managing hypoglycemia and, most importantly, on managing insulin pump therapy during intercurrent episodes." (PMID 40244428, 2025). "It has been shown that hypoglycemia activates the OX system and that OX-A can increase blood glucose and insulin levels, while OX-B only increases insulin levels." (PMID 40149526, 2025). "We present a case of recurrent hypoglycemia in a 53-year-old Caucasian female, attributed to insulin autoantibodies, which responded well to treatment with steroids and dietary modifications." (PMID 39968421, 2025). "This supports previous evidence that intensive insulin therapy, while essential for glycemic control, increases vulnerability to exercise-related hypoglycemia." (PMID 41030722, 2025). "The cornerstone of management includes timely fluid resuscitation with balanced crystalloids, insulin administration to inhibit ketogenesis, and glucose supplementation to prevent hypoglycemia, as was shown in EMCrit." (PMID 40585463, 2025). "Although GLP-1 RAs are considered safe as monotherapy, their glucose-dependent mechanism of insulin secretion means that hypoglycemia is rare unless combined with insulin or sulfonylureas." (PMID 41010364, 2025). "Some patients also expressed confusion about how to adjust insulin during illness, and a few charts referenced fear of hypoglycemia." (PMID 40755641, 2025). "A pivotal correlation was discerned between VPA and nocturnal hypoglycemia incidences at or above an insulin dose of 1.04 units/kg/day (P = .016)." (PMID 38954647, 2025). "This emphasizes the importance of monitoring by a professional trained in insulin adjustment when using LEDs and exercising caution in individuals with hypoglycemia unawareness." (PMID 40677318, 2025).
Hypoglycemia (continued). "In the postprandial state, GIP stimulates insulin after a meal and glucagon secretion during eu- and hypoglycaemia." (PMID 40218856, 2025). "Our findings of powerlessness and hypoglycemia fear as top stressors resonate with regional studies linking distress to limited access to advanced technologies (e.g., insulin pumps) and education in conservative healthcare settings." (PMID 41517010, 2025). "The use of SU has been proven safe and effective for at least 10 years of treatment and shows fewer risks of hypoglycemia than insulin injections." (PMID 41169283, 2025). "Another serious issue is hypoglycemia, particularly in older patients who use insulin or sulfonylureas." (PMID 41450405, 2025). "Unfortunately, psychological and practical barriers—most notably the fear of hypoglycemia and the burden of daily injections—often discourage timely insulin initiation." (PMID 40937414, 2025). "It is also recommended in insulin-treated non-T1DM populations with problematic, severe hypoglycaemia or labile glucose control for insulin titration and/or prevention of hypoglycaemia." (PMID 41157252, 2025). "Pharmacists reinforce adherence to prescribed regimens; address medication-related concerns such as medication side effects, insulin adherence barriers, insulin injection technique and drug-drug interactions; and mitigate hypoglycaemia fears." (PMID 40662123, 2025). "The addition of dextrose-containing fluids alongside insulin is often necessary to prevent hypoglycemia while enabling ongoing ketone clearance." (PMID 40376133, 2025). "The findings of the present study showed that low level of knowledge regarding insulin self-administration was a predictor variable for self-reported hypoglycemia." (PMID 40110390, 2025). "With an affinity for IR-A close to that of insulin, IGF-2 can exert mitogenic effects, but can also result in clinically significant hypoglycemia, particularly when present in circulating levels 100 to 1000 times that of insulin." (PMID 40270996, 2025). "The proportion of prescriptions for insulin, IIs, RIs, and SUs decreased between 2013 and 2022, similar to the incidence of hypoglycemia." (PMID 40777704, 2025). "Reduced insulin secretion is another counterregulatory mechanism to avoid hypoglycemia in adult GHR-KO pigs." (PMID 41125144, 2025). "We have extensively characterized the role of VMH GI neurons in the sympathoadrenal counterregulatory response to insulin-induced hypoglycemia." (PMID 40181907, 2025). "This reduced flexibility can result in a mismatch between insulin action and meal timing, increasing the likelihood of both mild and severe hypoglycemia." (PMID 40620795, 2025). "The repeated cycle of symptomatic resolution followed by recurrent hypoglycemia despite dextrose administration and the presence of a cystic pancreatic lesion on imaging heightened concern for an insulin-secreting tumor." (PMID 40757084, 2025). "Clinically, the patients with an insulinoma manifest primarily as episodic hypoglycemia, primarily due to excessive insulin secretion from the tumor tissue." (PMID 39935661, 2025). "Hypoglycemia is observed when GLP-1 receptor agonists are combined with insulin therapy, so clinicians and patients have to be attentive to reducing insulin dosages given the weight loss induced by GLP-1 receptor agonists." (PMID 41178712, 2025). "GLP-1RAs function in pancreatic beta cells to stimulate insulin secretion that depends on glucose levels, thus releasing insulin only when glucose concentrations rise and minimizing hypoglycemia risks." (PMID 40422559, 2025). "Hypoglycemia decreased this gene profile in each sex (SCR siRNA/INS [brown box-and-whisker plots; unfilled: male, stippled-filled, female] versus SCR siRNA/V [green box-and-whisker plots; unfilled: male, stipple-filled, female])." (PMID 40534773, 2025). "The existence of a tumor, coupled with diminished insulin and C-peptide levels amid recurrent fasting hypoglycemia, heightened the suspicion for NICTH." (PMID 41333493, 2025).
Hypoglycemia (continued). "In clinical practice, hypoglycemia (blood glucose falling below 3.9 mmol/L) is a frequently encountered complication in Type I diabetics on insulin therapy." (PMID 38965163, 2025). "Following the initiation of hybrid closed-loop insulin pump therapy, glycemic control improved (HbA1c 7.7%), and hypoglycemia episodes decreased." (PMID 41473654, 2025). "Preclinical studies demonstrate that “glucose-responsive” insulin expression systems can achieve sustained glycemic control while avoiding hypoglycemia, highlighting their therapeutic potential." (PMID 40869431, 2025). "This demonstrates that hybrid closed-loop insulin pump therapy effectively improved blood glucose control, reduced variability, and minimized hypoglycemia episodes over time." (PMID 41473654, 2025). "In order to prevent hypoglycaemia, it is advised to run 10% glucose concurrently once the blood glucose is <14 mM and to consider reducing insulin infusion to 0.05 units kg−1 h−1." (PMID 40480914, 2025). "In this mode, the glucose target and hypoglycaemia threshold are increased by 3.9 mmol/l, which reduces the aggressiveness of insulin delivery." (PMID 39653802, 2025). "Following admission, an insulin-induced hypoglycemia stimulation test indicated mild reduction in growth hormone axis function, while the cortisol axis showed compensatory function." (PMID 40529824, 2025). "Juvenile hypoglycemia in GH insensitivity results from excessive insulin sensitivity, reduced glucose production, and impaired lipolysis." (PMID 41125144, 2025). "These episodes were consecutively documented by endocrinology, with the patient and provider both noting that hypoglycemia occurred despite appropriate insulin dosing for carbohydrate intake." (PMID 41040769, 2025). "According to this guideline, for patients using SUs, GLs, and insulin, a higher target for HbA1c control was set to avoid hypoglycemia, and a lower limit was set." (PMID 40777704, 2025). "Such inappropriate insulin secretion can also suppress the production of ketone bodies, which serve as an alternative fuel for the brain during hypoglycaemia." (PMID 40265383, 2025). "After pituitary mass resection, intra-operative glucose monitoring is essential to avoid hypoglycemia given the abrupt reduction in insulin levels." (PMID 40385738, 2025). "It showed that women receiving insulin pumps had much better HbA1c levels, fewer severe hypoglycemic events by 35%, and fewer rates of neonatal hypoglycemia compared to women receiving insulin injections." (PMID 40125239, 2025). "One reported transient bilateral miosis in a patient with severe insulin-induced hypoglycemia, while another described prolonged reactive miosis following insulin intoxication." (PMID 40564809, 2025). "The ability of KATP channels to open in response to hypoglycemia is critical to preventing inappropriate insulin secretion." (PMID 40135739, 2025). "These technologies initially enabled the glucose-responsive regulation of insulin delivery to address hypoglycemia." (PMID 40565985, 2025). "Hypoglycaemia is the consequence of the interaction between absolute or relative insulin excess from treatment and compromised physiological defences against falling plasma glucose." (PMID 40520684, 2025). "It was therefore recommended that dogs exercise during the time period of 8–12 h after insulin administration and after the time of peak NPH action, to decrease the risk of hypoglycemia." (PMID 40612145, 2025). "Under hypoglycemia conditions, as observed in Gadd45a KO mice, insulin secretion by pancreatic β cells is increased." (PMID 40301189, 2025). "Clinical trials demonstrated that Afrezza provides rapid pulmonary absorption, non-inferior post-prandial glycemic control, and reduced late hypoglycemia compared with subcutaneous rapid-acting insulin analogs." (PMID 41463606, 2025).
Hypoglycemia (continued). "Metformin administration was linked to a reduced occurrence of neonatal hypoglycemia (RR 0.74) and NICU admission (RR 0.76) compared with the insulin group." (PMID 39860070, 2025). "When blood glucose levels dropped below 100 mg/dL, the insulin infusion was temporarily stopped to prevent hypoglycemia." (PMID 39931500, 2025). "Fos-nesfatin-1, double immunostaining was used to determine the combined effect of heterosexual pheromone challenge and insulin-induced hypoglycemia on neuronal activation in adults." (PMID 39859453, 2025). "Congenital hyperinsulinism (CHI) refers to genetic disorders characterized by persistent hypoglycemia secondary to inappropriately elevated insulin secretion." (PMID 40474078, 2025). "In another prospective trial, women randomized to metformin had lower mean glucose levels, less gestational weight gain, and neonates with lower rates of hypoglycemia than those randomized to insulin." (PMID 40235646, 2025). "First, elevated insulin concentrations promote cellular glucose uptake and glycogen synthesis, potentially leading to rebound hypoglycemia when the insulin effect peaks after glucose infusion is complete." (PMID 41463929, 2025). "Congenital hyperinsulinism (CHI) is a heterogeneous disorder of insulin dysregulation, leading to hypoglycemia." (PMID 40828772, 2025). "Insulinoma, a prevalent functional pancreatic neuroendocrine neoplasm (pNEN), is characterized by specific insulin secretion, leading to endogenous hyperinsulinemia and subsequently resulting in hypoglycemia." (PMID 39935661, 2025). "Current guidelines suggest the start of insulin therapy when there is persistent hyperglycemia (> 180 mg/dl) and avoidance of hypoglycemia (< 80 mg/dl)." (PMID 39838305, 2025). "Catecholamine release triggered by insulin-induced hypoglycemia can be inhibited by superior mesenteric ganglionectomy or capsaicin application to the hepatoportal vein, but not by vagal nerve transection." (PMID 40940782, 2025). "Serum samples were drawn for IGF-2, IGF-1, IGF binding protein 3 (IGFBP-3), insulin, proinsulin, and C-peptide prior to hypoglycemia correction." (PMID 40270996, 2025). "Key issues included hypoglycaemia due to excessive insulin or sulfonylureas dosing and persistent hyperglycaemia despite ongoing therapy." (PMID 40959457, 2025). "Although the total daily insulin doses were similar in both cases, patients using glargine experienced approximately 29% fewer episodes of hypoglycemia compared to those treated with NPH insulin." (PMID 40574081, 2025). "The GLP-1 receptor antagonist exendin-9-39 (avexitide), which blocks the effect of GLP-1, decreasing insulin secretion and mitigating hypoglycemia, has shown promising results in patients with post bariatric hypoglycemia." (PMID 41561059, 2025). "A comparison of hypoglycemia incidence based on insulin use history in the two study groups showed that hypoglycemia incidence significantly differed among patients with a history of insulin use (P < 0.001)." (PMID 40862101, 2025). "An 11-year-old boy began to present generalized tonic-clonic seizures in the presence of hypoglycemia, with high insulin dosage, leading to suspicion of insulinoma." (PMID 40136120, 2025). "Congenital hyperinsulinism (CHI) is a rare and potentially life-threatening disorder characterized by excessive insulin secretion, resulting in persistent and severe hypoglycemia." (PMID 40492016, 2025). "In another case report, despite a serum insulin concentration within the reference range, hypoglycemia was observed." (PMID 39030378, 2025). "Alarms and safety functions, such as suspension of insulin delivery, can help to reduce the hypoglycaemia burden." (PMID 40520684, 2025). "AfrezzaTM, a dry-powder, rapid-acting inhaled insulin, is FDA-approved, but causes hypoglycemia, throat irritation, cough, and bronchospasm in patients with asthma or chronic pulmonary disease, with low bioavailability (~24%)." (PMID 41463606, 2025).